CFTR (CF transmembrane conductance regulator)
Diseases named in the same sentence as CFTR in open-access papers (continued):
Sharing a sentence is not in itself a finding about the gene and the disease.
Infertility (continued). "In the 964 infertile couples examined, 132 subjects (69 women and 63 men) resulted heterozygous for one of the CFTR mutations, with a recurrence of carriers of 6.85%." (PMID 25304080, 2014). "Four of the HapMap nonsynonymous SNPs within CFTR are classified as deleterious, one of which has been associated with infertility." (PMID 21901107, 2011). "Additionally, oxidative stress-induced epigenetic changes and altered small RNA profiles in sperm from infertile men with CFTR variants have been proposed as molecular mechanisms warranting further exploration." (PMID 41009940, 2025). "In the validation study, ES was performed on DNA of patients already diagnosed with AZF deletions (n = 17), (non‐)mosaic sex chromosomal aneuploidies or structural chromosomal anomalies (n = 37), CFTR variants (n = 26), or variants in known infertility genes (n = 4), and 90 controls." (PMID 39180390, 2025). "An alternative approach could be utilizing well-characterized cohorts of individuals with CF for monitoring the spectrum and frequency of CFTR variants in the context of infertility assessments." (PMID 38254935, 2023). "This variant of the CFTR gene was found in a large cohort of 6,033 Russian infertile men." (PMID 38003474, 2023). "Our work seeks to assess the frequency of pathogenic CFTR variants identified in infertile men in Russian regions based on data from population studies and CF studies, including the results of individuals with CF genotyping and data from the Registry of Russian CF Patients." (PMID 38254935, 2023). "CFTR (cystic fibrosis transmembrane conductance regulator) is one of the most common genetic mutations leading to azoospermia, which can lead to abnormalities in the male reproductive tract and ultimately result in infertility." (PMID 37895049, 2023). "In addition to the well-known impacts of CF on the lungs and gastrointestinal system, infertility remains a common phenotype of patients with CFTR mutations." (PMID 37877879, 2023). "Thus, the allele frequency (AF) of L138ins in examined cohort of Russian infertile men was 0.15%, making it the third most common CFTR gene variant after F508del and CFTRdele2,3(21kb)." (PMID 37510311, 2023). "Hence, the objective of the present study was to investigate the most prevalent mutations in CFTR gene in Iranian infertile men (CBAVD and NOA)." (PMID 29986553, 2019). "We could not demonstrate an increased frequency of double heterozygosity of CFTR mutations among other studied groups of infertile men." (PMID 25386751, 2014). "Thus, it may be considered to apply the big panel with 32 mutations to only men with OA or maybe even only men with CBAVD/CUAVD, until further research shows if also other categories of infertile men should be examined for CFTR mutations and for which?" (PMID 33095972, 2021). "This section addresses the dual pathophysiological mechanisms of CF-related infertility—obstructive azoospermia and potential CFTR-mediated sperm dysfunction—while highlighting their clinical and mechanistic relevance." (PMID 41009940, 2025). "Managing infertility in men with CF or CFTR-related CBAVD requires more than surgical intervention or assisted reproduction." (PMID 41009940, 2025). "The possibility of undiagnosed CF or CFTR-RD should be taken into account in the examination of infertile men, especially in patients with obstructive azoospermia." (PMID 38003474, 2023). "With CF patients living longer and healthier lives with CFTR modulators, there is a growing need for continued discussion about infertility diagnosis and treatment options for CF patients who desire to conceive via assisted reproductive techniques." (PMID 37877879, 2023). "In 2002, Foresta and colleagues recommended karyotyping and molecular testing of FMR1, ANOS1 and CFTR in their ‘Guidelines for the appropriate use of genetic tests in infertile couples’." (PMID 35451369, 2022).
Infertility (continued). "This review focuses on molecular evidence that favors a role for CFTR in cryptorchidism-induced infertility." (PMID 35725394, 2022). "For instance, CFTR was shown to be involved in aromatase activation and estrogen production, both of which play important roles in infertility in women with endometriosis." (PMID 33613630, 2021). "Male genetic diagnostics for infertility comprise karyotyping, screening for AZF microdeletions, CFTR analysis and a gene panel including genes associated with CHH." (PMID 38836211, 2021). "We present the first report of longitudinal screening for CF on Sicilian infertile population by sequencing the entire CFTR gene by NGS." (PMID 32357917, 2020). "Although numerous investigations have revealed the relationship of CFTR gene with infertility problem in populations all over the world, a limited number of such studies have been published in males with CBAVD and other types of infertility in Iran." (PMID 29986553, 2019). "Three infertile males were subjected to semen analysis, hormone testing, testicular histology, ultrasonography, karyotyping, Y-chromosome microdeletion and CFTR testing." (PMID 30389958, 2018). "The current study also suggests avenues to understand the pathophysiology of CFTR during spermatogenesis and provides targets for the possible treatment of CFTR-related infertility." (PMID 27483469, 2016). "Distribution of CFTR and IVS8polyT genotypes in infertile men with different sperm counts and fertile controls." (PMID 25386751, 2014). "CBAVD is the most common CFTR-RD and accounts for 1–2% of the population of infertile, but otherwise healthy, males and up to 25% of those with obstructive azoospermia." (PMID 25386751, 2014). "Therefore, this is a CF-causing CFTR mutation that could be considered as a cause of infertility." (PMID 25246892, 2012). "The endometrium of infertile patients with hydrosalpinx had significantly higher NF KappaB mRNA and protein expression, and significantly lower CFTR and MUC1 mRNA and protein expression, compared to control infertile patients." (PMID 23061681, 2012). "Further studies are required to determine the expression and regulation of CFTR in the endometrium of infertile patients with hydrosalpinx." (PMID 23061681, 2012). "Taken together, these findings support the notion that while obstructive azoospermia remains the primary mechanism of infertility in CF, a broader spectrum of CFTR-related functional effects on sperm physiology may contribute to subfertility in select cases." (PMID 41009940, 2025). "Many men with CBAVD and infertility do not exhibit other clinical signs of CF; however, many of them carry compound heterozygotes with “severe” and “mild” CFTR mutations, and in most cases, the “mild” mutation is represented by the 5T allele." (PMID 40724872, 2025). "For example, men harboring certain combinations of CFTR mutations (often one mild and one severe, such as R117H paired with a 5T splice variant) may be otherwise healthy but have CBAVD leading to infertility." (PMID 41009940, 2025). "The classic sweat chloride test may show intermediate or mildly elevated values in men with CFTR-related infertility, reflecting reduced channel activity in epithelial tissues." (PMID 41009940, 2025). "The trans-combination of the 5T allele with “severe” mutation of the CFTR gene, such as F508del or R117H, may be a cause of CBAVD and infertility." (PMID 40724872, 2025). "Indeed, the percentage of heterozygous mutations associated with CFTR gene mutations in the Caucasian population is 5%, while the prevalence of CBVAD in infertile patients is 2%." (PMID 39124666, 2024). "The compound heterozygous CFTR mutations were first screened out by NGS in an infertile male patient who exhibited iCBAVD from a nonconsanguineous Chinese family." (PMID 37489040, 2023).
Infertility (continued). "Among the infertile men with CFTR mutations, 67% of those with azoospermia (lack of sperm in semen) and 37.5% of those with oligospermia (low sperm count) had these mutations." (PMID 37895049, 2023). "Thus, L138ins was found to be the second most common CFTR gene variant in Russian patients with CBAVD syndrome, and the third in prevalence after F508del and CFTRdele2.3(kb) in Russian infertile men." (PMID 38003474, 2023). "The CFTR mutation at one SNP (rs213950) was identified in seven of eight infertile men and one of two fertile controls, though when verified with Sanger sequencing, no fertile controls displayed this CFTR mutation." (PMID 37895049, 2023). "The CFTR gene is one of the genes confirmed to play a role in infertility." (PMID 35646184, 2022). "In male patients, the absence or severely reduced activity of CFTR protein can lead to excessive viscosity of the epididymal fluid associated with infertility and/or congenital bilateral absence of vas deferens (CBAVD)." (PMID 32357917, 2020). "Also, interestingly CFTR has been reported to regulate GnRH secretion and thereby regulate sexual maturation and infertility in CF women." (PMID 31842871, 2019). "The purpose of this study was to investigate the frequency of the most common mutations of the CFTR gene (F508, G542X, N1303K, G551D, and W1282X) in a population of infertile men with nonobstructive azoospermia (NOA) and CBAVD in Iran." (PMID 29986553, 2019). "While the CFTR contribution is the most common cause reported to date, there are still many infertile patients with idiopathic OA who have no identified genetic cause." (PMID 30389958, 2018). "The aim of this study was to estimate the frequency of ∆I507 and ∆F508 CFTR mutations in Iranian infertile males with non-obstructive azoospermia." (PMID 28042420, 2017). "For the interested reader, several recent reviews describe in detail the role of CFTR in anion (Cl− and HCO3−) and fluid transport in these tissues, together with diseases associated with defective CFTR, such as CF secretory diarrhoeas and infertility." (PMID 27714410, 2017). "We suggest that the interplay between SLC9A3 and CFTR is responsible for CF-related infertility." (PMID 28384194, 2017). "In infertile men, high-effect variants at acceptor splice site in CFTR were found in non-obstructive azoospermia, oligospermia, asthenospermia and teratospermia men." (PMID 27079378, 2016). "It is possible that the decreased CFTR expression observed in infertile patients with hydrosalpinx in our study may be the result of a compensatory effect." (PMID 23061681, 2012). "Although the patterns of expression of CFTR and NF KappaB have been reported in the endometrium, the role of these factors in the pathogenesis of hydrosalpinx and the relationship between these factors, hydrosalpinx and infertility are poorly characterized." (PMID 23061681, 2012). "Interestingly, in this study we observed that the expression level of CFTR was significantly lower in the endometrium of infertile patients with hydrosalpinx." (PMID 23061681, 2012). "Almost 40% of infertile men cases are classified as idiopathic when tested negative to the current diagnostic routine based on the screening of karyotype, Y chromosome microdeletions and CFTR mutations in men with azoospermia or oligozoospermia." (PMID 37540677, 2023). "Either way, the dual role of CFTR in the proximal male genital ducts provide at least two mechanisms, whereby loss of CFTR could lead to epididymis abnormalities, absence of the vas deferens, and associated infertility in CF males." (PMID 32855272, 2020). "Based on these investigations, to date, it remains uncertain whether screening of CFTR mutations should be recommended for infertile males with non-obstructive azoospermia during assisted reproduction technology." (PMID 28042420, 2017).
Infertility (continued). "In addition, several studies have shown increased frequencies of CFTR mutations in infertile patients with non-obstructive azoospermia, impaired spermatogenesis and low sperm quality." (PMID 25386751, 2014). "The consequences of CFTR dysfunction often manifest before birth and may include embryological abnormalities such as the Wolffian structure, resulting in the bilateral congenital absence of the vas deferens—a cause of infertility." (PMID 38611676, 2024). "After genetic counseling, several genetic-chromosomal analyses were carried out in the son (karyotype, chromosome Y microdeletions, CFTR screening, NGS infertility panels, and finally array-CGH)." (PMID 39259317, 2024). "Although these differences were not statistically significant, the higher percentage of CF mutations among infertile patients, especially those with obstructive azoospermia might imply a presence of some other mild CFTR-RD variant in these patients that was not investigated by our screening assay." (PMID 25386751, 2014). "The precise expression levels and role of CFTR, MUC1 and NF KappaB during the implantation window in infertile patients with hydrosalpinx remain to be explored." (PMID 23061681, 2012). "Increased NF KappaB expression and decreased CFTR and MUC1 expression in the endometrium of infertile patients with hydrosalpinx reinforce the involvement of a molecular mechanism in the regulation of endometrial receptivity." (PMID 23061681, 2012). "This study demonstrates that the expression of NF KappaB is significantly increased, while the expression of CFTR and MUC1 are significantly decreased in the endometrium of infertile patients with hydrosalpinx." (PMID 23061681, 2012). "Several studies have also reported CFTR variants in non-CAVD infertile patients, indicating that those with CFTR variants in general are at higher risk of infertility even without CAVD." (PMID 30214069, 2019). "We first evaluated the mRNA expression of CFTR in 46 of ovarian endometriotic lesions and 14 of normal endometria from the infertile patients without endometriosis." (PMID 28978008, 2017). "Interestingly, we observed a positive correlation between CFTR and MUC1 mRNA and a negative correlation between CFTR and NF KappaB mRNA in the endometrium of infertile women." (PMID 23061681, 2012). "Additionally, a negative correlation was observed between the levels of CFTR and NF KappaB mRNA expression in the entire cohort of infertile patients with and without hydrosalpinx (r = −0.59, P < 0.05)." (PMID 23061681, 2012). "Therefore, we examined the expression of CFTR, NF KappaB and MUC1 in endometrial tissues collected from infertile patients with or without hydrosalpinx, and analyzed the relationship between CFTR and NF KappaB or MUC1 expression in the endometrium tissues of infertile patients with hydrosalpinges." (PMID 23061681, 2012). "In addition, NGS analysis of the CFTR gene for heterozygous carriage could be recommended at the stage of pregnancy planning, as well as for male patients with obstructive or non-obstructive forms of infertility." (PMID 40724872, 2025). "Spearman’s correlation analysis demonstrated that a positive correlation existed between the expression of CFTR and MUC1 mRNA in the entire cohort of infertile patients with and without hydrosalpinx (r = 0.65, P < 0.05)." (PMID 23061681, 2012).
chronic obstructive pulmonary disease (62 papers, 2009 to 2026). A chronic and progressive lung disorder characterized by the loss of elasticity of the bronchial tree and the air sacs, destruction of the air sacs wall, thickening of the bronchial wall, and mucous accumulation in the bronchial tree. "Heterozygous carriers of mutationsin the cystic fibrosis transmembrane regulator (CFTR) geneare predisposed to idiopathic chronic pancreatitis (Weiss etal., 2005) and chronic obstructive pulmonary disease (Divacet al., 2004)." (PMID 36923482, 2023). "We, and others, have recently linked the loss of CFTR function to the development and progression of the chronic bronchitis (CB) form of chronic obstructive pulmonary disease (COPD)." (PMID 30547226, 2019). "Smoking-induced chronic obstructive pulmonary disease (COPD) is associated with acquired systemic cystic fibrosis transmembrane conductance regulator (CFTR) dysfunction." (PMID 24568560, 2014). "Finally, CFTR-positive ionocytes were less common in asthma and chronic obstructive pulmonary disease and were associated with airflow obstruction." (PMID 39255033, 2024). "TGF-β1 plays a significant role in the pathogenesis of other forms of lung disease, including chronic obstructive pulmonary disease (COPD), the third leading cause of death in the US, where it causes acquired CFTR dysfunction by cigarettes smoke exposure." (PMID 32481719, 2020). "Finally, CFTR plays an important role controlling fluid movement across several epithelia, and it has been implicated in a number of pathologies, including secretory diarrheas, chronic obstructive pulmonary disease, polycystic kidney disease, and others." (PMID 32934006, 2020). "Prominently, acquired CFTR dysfunction has been independently linked to chronic obstructive pulmonary disease (COPD), the third leading cause of death in the US and source of over $30 billion in annual healthcare costs." (PMID 28923049, 2017). "More recently, CFTR dysfunction has also been implicated in the pathogenesis of acute pancreatitis, chronic obstructive pulmonary disease (COPD), and the hyper-responsiveness in asthma, underscoring its fundamental role in whole body health and disease." (PMID 27714410, 2017). "Finally, these studies may be relevant to other chronic inflammatory lung diseases, particularly chronic obstructive pulmonary disease, which has been associated with systemic CFTR dysfunction." (PMID 28883468, 2017). "A widely described example is Chronic Obstructive Pulmonary Disease (COPD), which is associated with smoke-induced, sustained reduction in CFTR expression." (PMID 39043712, 2024). "S2, G to J), suggesting further investigation for treatment of other CFTR deficit–related respiratory diseases, such as chronic obstructive pulmonary disease." (PMID 38427726, 2024). "Furthermore, cigarette smoke (CS) was reported to downregulate CFTR mRNA expression and downregulation of CFTR expression has been associated with the development of chronic obstructive pulmonary disease (COPD)." (PMID 32326161, 2020). "Autophagy-CFTR dysfunction plays a vital role in regulating the pathogenesis of chronic obstructive lung diseases, including facilitating recurrent infections leading to severe disease exacerbations and an increased risk of mortality." (PMID 32847034, 2020). "There is a plethora of evidence in recent studies that a partial (in chronic obstructive pulmonary disease, COPD) or complete loss (in CF) of functional CFTR protein from the PM leads to reactive oxygen species (ROS)-mediated autophagy impairment." (PMID 30774592, 2019). "Examples include the HERG potassium channel and cardiac arrhythmia, the human peripheral membrane myelin protein 22 (PMP22) and Charcot-Marie Tooth disease, and a subset of mutations in the cystic fibrosis transmembrane conductance regulator (CFTR) protein." (PMID 31518351, 2019).